KLF9 (KLF transcription factor 9)
Diseases named in the same sentence as KLF9 in open-access papers (continued):
Sharing a sentence is not in itself a finding about the gene and the disease.
breast carcinoma (continued). "The devised in vitro experimental design has yielded prognostic gene signatures indicating reduced DMFS, identified KLF9 as a novel potential invasive growth suppressor in breast cancer and generated results in concordance with previous studies." (PMID 25593984, 2014). "All breast cancer samples (N=22, mean age: 59 ± 13) showed a significantly decreased expression of KLF9 in comparison with normal breast tissue (N=8, mean age: 45 ± 16)." (PMID 25593984, 2014). "Next to loss of expression in 6 out of 16 cancer types, KLF9 was shown to be significantly downregulated in breast carcinoma when compared to normal breast epithelium, applying P ≤ 0.01 and fold change ≥ 2 as thresholds (and TCGA Research Network)." (PMID 25593984, 2014). "We believe that the consistent subtype-independent downregulation of KLF9 in patient material confirms the relevance of this factor in human breast cancer." (PMID 25593984, 2014). "Putative involvement of KLF9 in breast cancer cell invasion was assessed in vitro by conducting a series of Transwell experiments on transiently transfected MDA-MB-231 cells after 24h." (PMID 25593984, 2014). "KLF9 also plays an important role in the regulation of key signaling pathways, including those related to hormone signaling and cell cycle control, underscoring its importance in breast cancer biology." (PMID 40860800, 2025). "Furthermore, the interactions between KLF9 with various microRNAs (such as miR-889) highlight its regulatory complexity and potential as a biomarker for breast cancer prognosis." (PMID 40860800, 2025). "In mouse and human fibroblasts as well as melanoma, colon, and breast cancer cell lines, the OS-induced expression of KLF9 leads to a further increase in intracellular ROS, as a consequence of KLF9 suppression of Thioredoxin Reductase 2 (TXNRD2; a key anti-oxidant protein) gene expression." (PMID 38067370, 2023). "Furthermore, evaluation of the genes constituting the prognostic invasion-related gene signature revealed Krüppel-like factor 9 (KLF9) as a putative suppressor of invasive growth in breast cancer." (PMID 25593984, 2014). "KLF9 over-expressing HEC-1-A cells had increased mRNA expression of BCAR3 and PSAT1, proteins previously implicated in the acquisition of tamoxifen resistance by breast cancer cells." (PMID 18783612, 2008). "Therefore, we screened a panel of breast cancer cell lines for KLF9-expression using RT-qPCR." (PMID 25593984, 2014). "First, Kleppel-like factor-9 (KLF9) can recruit HDAC1 to reduce the level of acetylation at the binding site of KLF9 to the matrix metallopeptidase 9 (MMP9) promoter, thereby inhibiting the invasion and migration of breast cancer cells." (PMID 38584203, 2024). "Among them were major regulators of breast cancer cell proliferation, including CCND1, LEF1, KLF9, GREB1, or MAP3K3." (PMID 36076907, 2022). "For example, KLF9 has been shown to enhance the expression of PTEN, a well-characterized tumor suppressor, thereby inhibiting aerobic glycolysis and reducing chemotherapy resistance in breast cancer cells." (PMID 40860800, 2025).
gastric cancer (13 papers, 2019 to 2025). A primary or metastatic malignant neoplasm involving the stomach. "For example, Kruppel-like factor 9 (KLF9) suppresses gastric cancer cell invasion and metastasis by inhibiting MMP28 expression." (PMID 39972459, 2025). "This mechanistic cascade positions KLF9 as both a miRNA-regulated target and a transcriptional activator in gastric cancer progression." (PMID 40860800, 2025). "In gastric cancer, KLF9 has been identified as a transcription factor that suppresses cell invasion and metastasis." (PMID 40860800, 2025). "With respect to gastric cancers, KLF9 is reported to be stimulatory or inhibitory to cancer cell proliferation and their invasive ability." (PMID 38067370, 2023). "The results of the analyses revealed that KLF9 expression was also decreased in gastric cancer tissues compared with normal gastric tissues." (PMID 36386179, 2022). "Next, the expression of KLF9 in gastric cancer tissues and adjacent tissues was analyzed by GEO dataset (GSE13195, GSE27342, GSE63069, and GSE65801) and TCGA database." (PMID 36386179, 2022). "We used multiple databases to carry out enrichment analysis of FNDC5-expressed genes and found that the expression level of KLF9 in gastric cancer patients was favorably correlated with FNDC5." (PMID 36386179, 2022). "Functionally, the TPTEP1/miR-548d-3p/KLF9/PER1 axis reduces gastric cancer cell migration and invasion, with KLF9 serving as the critical regulatory node that translates the long non-coding RNA TPTEP1’s tumor-suppressive effects into PER1-mediated anti-metastatic activity." (PMID 40860800, 2025). "It has recently been found that KLF9 was able to inhibit the migration and invasion of gastric cancer cells and suppress tumor metastasis in vivo, which may be associated with the transcriptional regulation of MMP28." (PMID 34564711, 2021). "Furthermore, KLF9 contributes to FNDC5-mediated tumor suppression in gastric cancer." (PMID 40860800, 2025). "KLF9 is obviously downregulated in patients with gastric cancer (GC) and KLF9 significantly inhibits the invasion and metastasis of GC cells through inhibiting the MMP28 transcription." (PMID 34612136, 2021). "Therefore, KLF9 may play a vital role in regulating the expression of FNDC5 in gastric cancer." (PMID 36386179, 2022). "Research has demonstrated that KLF9 expression is significantly reduced in metastatic gastric cancer tissues compared to non-metastatic counterparts." (PMID 40860800, 2025).
glioblastoma (13 papers, 2013 to 2025). The most malignant astrocytic tumor (WHO grade IV). "KLF9 is an evolutionarily well-conserved transcriptional regulator implicated as a tumor/metastasis suppressor in liver, endometrium, colon and rectum, breast, glioblastoma, ovary, and osteosarcoma." (PMID 35406507, 2022). "The dual therapeutic and mechanistic roles of KLF9 in glioblastoma underscore its potential role as a molecular switch to reprogram tumor stemness and therapy resistance." (PMID 40860800, 2025). "KLF9 plays a multifaceted role in glioblastoma, particularly in modulating stemness and tumor aggressiveness." (PMID 40860800, 2025). "In glioblastoma and ovarian cancer, KLF9 was shown to repress the expression of the Notch 1 gene, thereby resulting in reversion away from the stem cell phenotype due to less active Notch signaling." (PMID 38067370, 2023). "Further regulators of CD49f expression include positive regulation by Oct4 and Sox2 in mesenchymal stem/stromal cells and negative regulation by KLF9 in glioblastoma stem cells, which is important for repressing CD49f expression and glioblastoma stemness." (PMID 36246104, 2022). "This is consistent with a recent study in glioblastoma cells that showed that Klf9 functions primarily as a transcriptional repressor." (PMID 28407733, 2017). "In glioblastoma-derived neurospheres enriched with cancer stem cells, KLF9 was found to induce cell differentiation, suppress neurosphere formation, and inhibit xenograft growth by binding to the Notch1 promoter to repress Notch1 expression and downstream signaling." (PMID 40860800, 2025). "KLF9 suppressed Notch-1 transcription in glioblastoma multiforme derived from neurospheres." (PMID 37308977, 2023). "Over-expression of KLF9 suppressed glioblastoma cell stemness, in part, by repressing transcription of members of multiple signaling pathways that promote oncogenesis and stem cell phenotype, i.e., integrin, CXCR4 (C-X-C Chemokine Receptor Type 4), and Notch pathways." (PMID 38067370, 2023). "The KLF9 is known to suppress Notch1 signaling and inhibit glioblastoma-initiating stem cells." (PMID 36231068, 2022). "Additionally, KLF9 directly suppresses Notch1 expression and its downstream signaling which promotes differentiation and inhibits glioblastoma neurosphere growth." (PMID 24349493, 2013). "Additionally, studies suggest that the regulatory role of ITGA6 on glioblastoma stemness may be controlled by Kruppel-like factor-9 (KLF9)." (PMID 39239559, 2024). "KLF9, when synergized with the histone deacetylase inhibitor panobinostat (LBH589), induces cell death in glioblastoma stem-like cells (GSCs)." (PMID 40860800, 2025). "KLF9 (and to a lesser degree KLF13) represses the cancer stem cell phenotype in glioblastoma and ovarian cancer, and thus, perhaps other cancers as well." (PMID 38067370, 2023).
hepatocellular carcinoma (12 papers, 2019 to 2025). A malignant tumor that arises from hepatocytes. "By promoting oxidative stress and inflammation in mice fed a high-fat Diet, KLF9 suppresses hepatocellular carcinoma progress." (PMID 36359788, 2022). "KLF9 expression was found to be reduced in hepatocellular carcinoma (HCC) compared to surrounding normal liver tissue; moreover, KLF9 inhibited cell proliferation and mobility and induced apoptosis of HepG2 cells in vitro." (PMID 35406507, 2022). "In hepatocellular carcinoma (HCC), KLF9 reportedly plays a protective role against tumor progression." (PMID 40860800, 2025). "In addition, in hepatocellular carcinoma, the PDCD5 overexpression stimulates the promoter activity of KLF9, and the upregulation of KLF9 inhibits cell migration and proliferation." (PMID 36033519, 2022).
prostate carcinoma (11 papers, 2015 to 2025). A carcinoma that arises from epithelial cells of the prostate gland. "KLF9 knock-down caused an increase in prostate cancer cell spheroid formation, the latter an index of cancer stem cell phenotype." (PMID 38067370, 2023). "Targeting by miR-141-3p of the 3′ UTR of KLF9 mRNA may underlie tumor-mediated loss of KLF9 expression since this miRNA is induced in prostate tumors, and moreover, enhances sphere formation by prostate cancer cells in vitro." (PMID 38067370, 2023). "KLF9 is a potent growth suppressor in prostate cancer cell lines in vitro and this involves, in part, the repression of two major pathways, namely those for AKT and the androgen receptor (AR), along with the induction of apoptosis." (PMID 38067370, 2023). "KLF13 is a suppressor of prostate cancer cell growth in vitro and of xenografts in mice, and like KLF9, suppresses AKT signaling and promotes apoptosis." (PMID 38067370, 2023). "Conversely, KLF9 was reported to suppress androgen receptor (AR) expression in prostate cancer cells, highlighting its growth inhibitory effects on androgen-dependent tumor cells." (PMID 38067370, 2023). "Conversely, KLF9 works as a transcriptional repressor inhibiting AKT transcription in prostate cancer cells, thereby suppressing the growth of PCa cells." (PMID 37737576, 2023). "For example, miR-141-3p promoted prostate cancer cell proliferation by inhibiting Krüppel-like factor-9 (KLF9) expression." (PMID 36497250, 2022). "KLF9 has been suggested to play a role in the progression of prostate cancer to a castration-resistant stage." (PMID 26412853, 2015). "Moreover, miR-141-3p is upregulated in prostate cancer and can promote prostate cancer cell proliferation by inhibiting KLF9 expression." (PMID 34876902, 2021). "The miR-141-3p/KLF9 axis promotes the growth of prostate cancer." (PMID 33204711, 2020). "For example, miR-141 could promote prostate cancer cell proliferation through inhibiting KLF9 expression while it can also inhibit vascular smooth muscle cell proliferation through targeting PAPP-A or ZEB2 to suppress HCC progression." (PMID 29029425, 2017). "KLF9 and KLF13 both regulate the differentiation and proliferation of fat cells internally and can serve as potential therapeutic targets for prostate cancer cell proliferation." (PMID 39272379, 2024). "Both KLF9 and KLF13 inhibit the activation of the AKT signaling pathway, thereby suppressing the growth of prostate cancer cells." (PMID 39272379, 2024). "One of the studies validated the involvement of KLF9 in the Akt pathway and indicated that KLF9 substantially inhibits AKT activation and abrogates tumor growth in prostate cancer." (PMID 35047407, 2021).
colorectal cancer (10 papers, 2014 to 2025). A primary or metastatic malignant neoplasm that affects the colon or rectum. "KLF9 mRNA transcription and protein levels were decreased in colorectal cancer, and total or partial loss of KLF9 could promote colon tumorigenesis." (PMID 36301038, 2022). "For instance, in colorectal cancer, KLF9 concurrently regulates Wnt inhibition and PAD4-mediated metabolic reprogramming, yet the synergistic effects between these actions remain undefined." (PMID 40860800, 2025). "The inhibitory effect of KLF9 on IFN-induction of these genes was recapitulated in vitro using a human colorectal cancer cell line (HT-29)." (PMID 38067370, 2023). "Compared with normal mucosal cells, the abnormally low KLF9 level in colorectal cancer tissues was correlated with tumor stage." (PMID 34612136, 2021). "Reduced expression of KLF9 has been shown on a transcriptional as well as protein level in colorectal cancer samples when compared to paired normal mucosa." (PMID 25593984, 2014). "The literature regarding KLF13 and colorectal cancer is much less robust than that for KLF9." (PMID 38067370, 2023). "Similarly, in human colorectal cancer cell lines, use of 5-aza-2′-deoxycytidine revealed KLF9 as a methylation-silenced gene." (PMID 38067370, 2023). "Indeed, KLF9 KO mice show increased incidence of colorectal cancer." (PMID 34265306, 2021). "In colorectal cancer (CRC), KLF9 exhibits a tumor-suppressive role, evidenced by its downregulated expression in cancerous tissues compared to normal tissues." (PMID 40860800, 2025). "KLF9 was identified as a key component of a 4-gene prognostic signature (MCM2, INHBA, CGREF1, KLF9) for early-onset colorectal cancer (EOCRC)." (PMID 40860800, 2025).
glioma (9 papers, 2017 to 2025). A benign or malignant brain and spinal cord tumor that arises from glial cells (astrocytes, oligodendrocytes, ependymal cells). "KLF9 is known for its ability to inhibit the self-renewal of glioma stem cells and the growth of tumor xenografts in vivo." (PMID 39062119, 2024). "miR-940 also is inversely associated with KLF9 mRNA, and interestingly, the knock-down of KLF9 attenuated the positive effects of miR-940 on glioma cell proliferation and invasion in vitro." (PMID 38067370, 2023). "KLF9 expression is markedly reduced in gliomas, and glioma patients with higher KLF9 expression in their tumors survived longer than those with lower tumoral KLF9 expression." (PMID 38067370, 2023). "Forced expression of KLF9 inhibited glioma cell proliferation in vitro and tumor growth in vivo, in part, by suppressing expression of SOD1 (Superoxide Dismutase 1) and miR-21, the latter being a known pro-tumorigenic molecule." (PMID 38067370, 2023). "In glioma cells, KLF9 was identified to suppress the expression of SOD1, accomplishing the regulatory effects of GPR17 on ROS level." (PMID 34120140, 2021). "Subsequently, it was found that KLF9 promotes the differentiation of adipocyte in 3T3-L1 cells and glioma stem cell death." (PMID 32316525, 2020). "We demonstrated that KLF9 expression combined with HDAC inhibitor panobinostat (LBH589) dramatically induced glioma stem cell death via both apoptosis and necroptosis in a synergistic manner." (PMID 30348136, 2018). "To test our hypothesis, we firstly analyzed the survival curves of the glioma patients with high or low KLF9 expression from TCGA database, and found that patients with high KLF9 expression survived longer than patients in the other group." (PMID 34120140, 2021). "Like KLF9, KLF13 was shown to inhibit glioma cell proliferation and invasion in vitro, and moreover, patients with higher tumoral KLF13 expression had a better prognosis than those with lower KLF13 expression." (PMID 38067370, 2023). "As the role of KLF9 in oxidative stress has been widely reported, we therefore chose KLF9 as a downstream target for GPR17 and RNF2 to control ROS level in glioma cells." (PMID 34120140, 2021). "KLF9 could regulate the growth of tumor stem cells through the Notch1 signaling pathway, induce the differentiation of neural bulb cells and suppress the growth of tumor stem cells in glioma extended neural bulb cells, and it was low expressed in clinical glioma tissue samples." (PMID 34612136, 2021). "Another study reported that within the NF-κB-RNF2-KLF9 cascade, KLF9 serves as a key downstream effector mediating GPR17’s antiproliferative and pro-apoptotic roles in glioma pathogenesis, offering a dual targeting strategy involving GPR17 activation or KLF9 modulation." (PMID 40860800, 2025). "In neurosphere cultures of glioma tumor cells and tumor stem cells, the combined application of the zinc finger transcription factor krüppel-like factor 9 (KLF9) and the histone deacetylase inhibitor panabinostat (LBH589) led to cell death of glioma stem cells by apoptosis and necroptosis." (PMID 39062119, 2024). "KLF9 mediates the functions of GPR17 and RNF2 in glioma cells." (PMID 34120140, 2021). "Therefore, we hypothesized that KLF9 might mediate the regulatory effects of GPR17 and RNF2 on ROS levels and glioma tumorigenesis." (PMID 34120140, 2021).